PTGS2 (prostaglandin-endoperoxide synthase 2)
Diseases named in the same sentence as PTGS2 in open-access papers (continued):
Sharing a sentence is not in itself a finding about the gene and the disease.
tumor (continued). "The results of single-cell mRNA sequencing show PMEPA1 were mainly expressed in basal tumor cells and CAFs, TGFB1 were mainly expressed in basal tumor cells, CAFs and TAMs, PTGS2 were hardly expressed in those cells." (PMID 34777336, 2021). "Especially in the tumor tissue of LUAD, both IRF5 and NOS2 show significant correlations with LPAR6 expression and PTGS2 shows a significant correlation with LPAR6 expression in the tumor tissue." (PMID 34769557, 2021). "qRT-PCR data confirmed that PGE2 expression-related genes including Ptgs1, Ptgs2, Hpdgs, and Hpdg were relatively higher in DXM/lactoferrin PMN-MDSCs compared to tumor PMN-MDSCs in the mouse model." (PMID 33637832, 2021). "The result of q-rtPCR showed that the mRNA expression levels of PTGS2, RRM2, AURKA, CAV1, MAP3K5, STEAPS are higher in tumor samples and lower in normal tissue samples and the others had the reverse tendency." (PMID 33819918, 2021). "GGCT expression was significantly upregulated in tumor tissues, while AOX1, NT5E, PPP1R12A, and PTGS2 were significantly downregulated compared to normal tissues in the TCGA cohort." (PMID 34484299, 2021). "Increased expression of PTGS2 and production of PGE2 are found in many solid tumours, including HNSCC, and correlate with tumour stage, metastasis and worse clinical outcome, whilst low levels are associated with better response to chemotherapy." (PMID 33359448, 2021). "A number of interferon-stimulated genes (ISGs) were found to be highly induced in tumor compared to non-tumor samples, such as GBP1, CAMP, PTGS2, GOLIM4, IFIT3, MX1, LTF, and CYBB." (PMID 34400640, 2021). "Consistently, Ptgs2 and Hpdgs, were relatively higher in DXM/lactoferrin PMN-MDSCs compared to tumor PMN-MDSCs from human samples." (PMID 33637832, 2021). "Similar to our observation in tumor-bearing mice, PNZ tumor cells showed much stronger expression of PTGS2 when examined via immunohistochemical staining, indicating the occurrence of ferroptosis in this area." (PMID 33110073, 2020). "We found an upregulation for the PTGS2 gene mean factor of 2.51 and a downregulation for the HPGD and SLCO2A1 genes (mean factor of 0.10 and 0.37, respectively) in tumorous mucosa in a gender-independent manner." (PMID 33081378, 2020). "In vitro, celecoxib (PTGS2 inhibitor) or exogenous prostaglandin E2 (PGE2, an enzymatic product of PTGS2) failed to affect the growth of Gpx4−/− PDAC cells, indicating that the PTGS2 pathway may not be important for tumor growth associated with GPX4 depletion (Supplementary 3g)." (PMID 33311482, 2020). "Both tumor‐infiltrating neutrophils and monocytes expressed Arginase 2, CD39 and CD73, IL10, iNOS, and Ptgs2 at increased levels compared to circulating cells." (PMID 31793740, 2020). "We validated the downregulation of PTGS2 and CXCR4 with MDM2 and MDMX knockdown in the tumors by performing qRT-PCR from the sets of primary tumor samples." (PMID 30642351, 2019). "PTGS2 is overexpressed in TNBC, and promotes metastasis by regulating crucial molecules (Bcl-2, MRP4, PGT, 15-PGDH, TGFβ, etc.)involved in multiple tumor-promoting signaling pathways." (PMID 31690011, 2019). "The genes that were overexpressed in both senescent thyrocytes and at least one tumor cell line included genes coding for: the chemokines CCL3 and CCL-4, the cytokine IL-1β, the matrix-related protein SPP1, and the enzyme PTGS2." (PMID 31113465, 2019). "BRAF mutation determines an upregulation of the RAF-MAPK pathway, which leads to downstream activation of PTGS2 (COX-2) and to the increase of PGE2 production; this leads to higher survival and faster replication of tumor cells." (PMID 31661924, 2019). "Upregulation of Ptgs2 and Cxcl2 was confirmed in additional KPC tumor-derived B cells and was also observed in orthotopic B cells." (PMID 30972056, 2019).
tumor (continued). "Although the expression levels of PTGS2, ACTB, and MAPK4 are reduced by IGF2BP1 interfering with their mRNA translation, there are different results on tumor events." (PMID 29954406, 2018). "Then, prostaglandin G/H synthase 2 (PTGS2, degree = 10) is simultaneously targeted by 10 active compounds, and has high expression in various tumors, which can promote tumor growth and regulates inflammatory response." (PMID 30618763, 2018). "The synthesis of tumor-promoting prostaglandins is regulated not only by PTGS-2, but also by the PGE2-catabolizing enzyme HPGD, which acts as a physiological antagonist to PTGS-2." (PMID 28143522, 2017). "The identification of predictive genetic markers in PTGS2, IL4 and PIK3CA highlights, for the first time, the relevance of tumour microenvironment, inflammatory response and PI3K/AKT pathway activation in sunitinib treatment resistance." (PMID 28117391, 2017). "Cyclooxygenase-2 (COX-2), known as prostaglandin-endoperoxide synthase 2 (PTGS2), is a rate-limiting enzyme produced during the production of prostaglandins, and prostaglandins play an important role in inflammation, tumor progression, and metastasis." (PMID 24023834, 2013). "Epidemiological, clinical, and animal studies provide evidence demonstrating that PTGS2 (COX-2) plays a key role in promoting CRC progression, whereas inhibition of PTGS2 (COX-2) prevents tumor growth and improves overall survival." (PMID 24213116, 2011). "The inhibitory activity of IL13, IL1b, PTGS2, NOS2, and CTLA4 on the immune response would enhance tumor growth." (PMID 22013484, 2011). "By day 7, IFNγ, CSF2, CXCL10, GZMB, PTGS2, TNFα, CD80, CCL22, IL12a, IL13, IL1b, IL6, NOS2, and CTLA4 were significantly upregulated in the tumor-bearing mice bladders and AGTR2 and GATA3 were downregulated." (PMID 22013484, 2011). "The importance of this NK cell–cDC1 axis has been well demonstrated in tumor models lacking the Ptgs1 and Ptgs2 genes, which are required to produce the immunosuppressive prostaglandin PGE2." (PMID 40410571, 2025). "Last, NK cells were also rescued in RTTPtgs1/2 KO tumours and in IRF3/7 overexpressing tumours, but NK cell depletion in Ptgs2 KO tumours did not significantly change the infiltration of cDCs and T cells or overall tumour control in our models." (PMID 39604727, 2025). "The results showed that compared with the oe-LOC610012 + NC-pCDNA3.1 (+) group, the overexpression of PTGS2 in oe-LOC610012 cells partially restored the migration and invasion abilities of tumor cells and significantly reduced the increase in ROS induced by LOC610012 overexpression." (PMID 40643495, 2025). "The results demonstrated that the protein and mRNA levels of NFE2L1 and GPX4 were significantly increased in tumor tissues, whereas the ferroptosis marker proteins PTGS2, and CHAC1 were expressed at low levels in tumor tissues, however, SLC7A11 exhibited significant overexpression in tumor tissues." (PMID 41189569, 2025). "In CRC, PTGS2 expression is markedly promoted in tumor samples versus normal colorectal tissues and tightly associated with poorer CRC-specific survival." (PMID 38778047, 2024). "Key differentially expressed genes included PTGS2 (pro/antitumor), FOSL1, TNFRSF9, IL1B, DIO2, and PHLDA1 (antitumor), along with under-expressed genes with pro-tumor effects that may inhibit proliferation." (PMID 39409923, 2024). "With these findings in our study, the sh-RUNX1 vector appears to represent a potential anti-CRC agent that might function as a suppressor on tumor growth and metastasis in CRC by silencing PTGS2." (PMID 38778047, 2024). "We found that the IL22RA2 mRNA was decreased, while PTGS2 mRNA was significantly increased in tumors compared with non-tumor tissues." (PMID 36932082, 2023).
tumor (continued). "We also quantified the expressions of a ferroptosis marker gene PTGS2 and NRF2 downstream genes HMOX1 and TFRC in tumor tissues and found their expressions were all elevated by IKE treatment in mice received a control diet, but not in mice receiving methionine-free diet." (PMID 37553341, 2023). "Subsequent analysis of ferroptosis marker prostaglandin-endoperoxide synthase 2, GSH, MDA, and MUFA OA levels confirmed the role of SLC25A22 in inhibiting RSL3-induced ferroptosis in isolated tumor." (PMID 37051693, 2023). "Similarly, compared to that in peritumor tissues, the expression of ferroptosis-inducing genes, including PTGS2, HMOX1, TFR2, and NCOA4, was down-regulated in tumor tissues, whereas ferroptosis-suppressor genes SLC7A11 and FTH1 were upregulated." (PMID 37554285, 2023). "PTGS2 (COX-2) is an important mediator in promoting inflammation and tumor growth." (PMID 35855823, 2022). "In tumors derived from both cell lines, we found eicosanoid synthases (Ptgs1, Ptgs2, Hpgds, Alox5) to be more highly expressed in immune cells than in tumor cells although expression is not exclusive (Figure A3A and B; Table A2)." (PMID 36277993, 2022). "We then analyzed the associations between CXCL2 expression and classical macrophage phenotype markers of M0 (undifferentiated) (AIF1), M1 (anti-tumor) (IL12A, TNF, NOS2, PTGS2) and M2 (tumor-promoting) (IL10, CD163, TGFB1, CSF1R) in TCGA-LIHC cohort with Spearman’s rank correlation test." (PMID 36276119, 2022). "Under expression of PTGS2 (READ) and PDGFRA (COAD and READ), over expression of MET & MMP9 (COAD and READ) were observed in the expression analysis using boxplots of genes between normal and tumor samples." (PMID 36110531, 2022). "In contrast, FANCD2, PTGS2, SLC2A1, and SQLE were higher in tumor compared to normal tissues." (PMID 36733386, 2022). "In isolated tumors, simultaneous IF staining analysis of PTGS2 discovered that the combination of anti-PD-1 antibody and ICG001 indeed induced more tumor cell ferroptosis, and liproxstatin-1 coadministration could suppress the synergized therapeutic influence." (PMID 36429010, 2022). "Our findings are in accordance with the previous statements, as we found that both ADMSC and mature adipocytes secrete factors that could contribute to tumor development like IL6, EGF, PTGS2 and IL4 in ADMSC, and CCL5, IL1β and IGF in adipocytes." (PMID 33801973, 2021). "TGFB1, IL1B, IL10, IL6, PTGS2, and PPARG closely interacted with the tumor microenvironment." (PMID 34394377, 2021). "The CD8-positive tumor-infiltrating lymphocytes counts were inversely correlated with intra-tumoral PTGS2 expression in patients with lymph node-negative LUAD." (PMID 35096012, 2021). "The influence of PTGS2 expression on patient prognosis could be a possible criterion, but the quantification of PTGS2 by IHC only in CRC tumor cells showed variable results." (PMID 32168749, 2020). "In tumour ECs, VEGF-A and PFKFB3 play a major role in enhancing EC metabolism since inhibition of Prostaglandin endoperoxide synthase 2, also known as cyclooxygenase-2 (COX-2) decreases the expression of VEGF-A and PFKFB3 and reduces the glycolysis rate to the level of normal ECs." (PMID 32911833, 2020). "In fact, CXCR4, SPP1, ACKR3, CCL2, PTGS2, CD274 (PD-L1), CXCL11 were upregulated while CCL28, CCR1, CCR7 were down regulated in both comparisons (blue boxes), suggesting this as a signature specific of the core region of the tumor." (PMID 33066172, 2020). "Moreover, studies have shown that high level of PTGS2 can inhibit tumor growth and migration by regulating 8‐HOA, another derivative of PTGS2." (PMID 32556504, 2020).
tumor (continued). "Transmigration of tumor cells through the BBB is mediated by the upregulation of three genes: (HBEGF (Heparin-Binding Epidermal growth factor-like Growth Factor), COX-2 (PTGS2, Prostaglandin-Endoperoxide-Synthase-2), and ST6GALNAC5 (ST6-N-Acetylgalactosaminide-Alpha-2,6-Sialyltransferase-5))." (PMID 32645833, 2020). "Indeed, treatment of ApcMin/þ mice with celecoxib, the prostaglandin-endoperoxide synthase 2 selective inhibitor, or the EP4 receptor (prostaglandin receptor) antagonist ONOAE-208 resulted in a reduction of tumor CD133+CD44+ cells and tumor burden." (PMID 30967773, 2019). "Principle component analysis (PCA) was used to reduce the dimensionality of the TCGA-COAD and READ data sets for the tumor and normal samples, as well as for sigmoid and transverse normal colon samples, based on the expression of PTGS1, PTGS2, PTGES3, and TERT." (PMID 31614548, 2019). "Moreover, enhancers of migration and angiogenesis such as GPNMB, PTGS2, CD274, and ZNF703 were significantly downregulated suggesting suppression of tumor malignancy." (PMID 31842391, 2019). "However, our results also indicate that the tumor microenvironmental immune profile, defined by IL10 or PTGS2 gene expression levels, seems to alter the prognostic potential of CD20/MS4A1." (PMID 30879106, 2019). "The classifier could not be applied to predict survival based on expression of AURKA, PTGS2 and MMP9 in the primary tumor." (PMID 26497206, 2016). "Since RGS4 was up-regulated and PTGS2 was down-regulated in IMP1-expressing cells and xenografts, the data indicated that the function of IMP1 in suppressing tumor cell proliferation and invasion could through the regulation of its bound mRNAs." (PMID 26910917, 2016). "We then analyzed whether the PTGS2 and PTGES are co-expressed/co-induced in cancer cells calculating the Pearson correlation coefficient of their gene expression values for each tumor sample." (PMID 26498686, 2015). "Likewise, mRNA levels of Ifit1 and Ifit2, two type I IFN-stimulated genes (ISGs), were also elevated in Ptgs2−/− tumors, indicative of enhanced type I interferon (IFN-α/β) signaling, which is central to immune-mediated tumor control." (PMID 26343581, 2015). "The tumor cells express functional receptors for growth factors, cytokines, chemokines, and other molecules involved in the angiogenic and inflammatory processes including VEGF, IL-6, IL-8, CXCL12, and PTGS2 (COX-2)." (PMID 29061946, 2015). "SL exposure also induced changes in the expression of genes involved in metabolic functions in tumor and stem cells (ALDH1B1, ABCB1, SLC3A2, SLC44A2, SLC31A2, SLC7A11, CYP24A1, PTGS2/COX2, PPRC1), cytokines (CCL3L3, GDF15) and growth and differentiation factors (PGF, TGFBR11 and FOXD1)." (PMID 24742967, 2014). "Another study analyzed whole blood samples from 76 CRPC patients, treated by maximum androgen blockage, in order to detect circulating tumor cells (CTCs) and methylated DNA (using qMSP) for a five-gene candidate marker panel (GSTP1, APC, PTGS2, MDR1 and RASSF1A)." (PMID 25238417, 2014). "We found that xenograft tumours from mice treated with SP had significantly elevated expression of PTGS1 and PTGS2 mRNA compared to controls (3.1±0.1 fold; P<0.01 and 6.2±0.2 fold; P<0.001 for SP vs control for PTGS1 and PTGS2 respectively)." (PMID 22442729, 2012). "IL10, PTGS2, and FASL are known to suppress the immune response and SMAD7 which inhibit TGFβ, and bone morphogenetic protein expression was downregulated which would lead to an environment favoring tumor growth." (PMID 22013484, 2011). "PTGS2, also called COX-2, plays an important role in tumor and endothelial cell biology." (PMID 18726958, 2008). "After analyzing the methylation levels of the genes that were differentially methylated among the four tumor subtypes, empirical cutoff values were established to maximize the discriminative power of each gene (2.0 for CDH1, 80.0 for PTGS2, and 230.0 for RASSF1A)." (PMID 17645803, 2007).
tumor (continued). "Also, other genes (PTGS2, RAC1, and ACTN1) that are involved in tumor metastasis were found to be significantly upregulated in the CAM-DOX SH-SY5Y cells as compared to CTRL, which could be implicated in their mobilization and metastasis." (PMID 40032892, 2025). "In the metastasis group, the top shared upregulated genes were cancer-related with diverse functions, including tumor suppressors (SAMD9 and SEMA3B) and genes involved in growth, survival, cytoskeletal dynamics, motility, invasion, and metastasis (RHOBTB3, CYP24A1 and PTGS2)." (PMID 40605119, 2025). "Therefore, Ptgs2−/− cell lines showed no cell-autonomous defects in tumor progression but were instead sensitized to antitumor immune responses, with immunologic rejection occurring in a substantial proportion of mice." (PMID 38635884, 2024). "These genes, including ERBB2, CCNA1, FOXC2, LEFTY2, VTN, ACKR3, and PTGS2, are involved in key processes like apoptosis, epithelial–mesenchymal transition, angiogenesis, response to hypoxia, and KRAS signaling pathways, which are crucial for tumor virulence and the spread of metastases." (PMID 39000413, 2024). "Among these genes are ERBB2, CCNA1, FOXC2, LEFTY2, VTN, ACKR3, and PTGS2, which influence processes such as apoptosis, epithelial–mesenchymal transition, angiogenesis, hypoxia responses, and KRAS signaling pathways, all vital for tumor aggressiveness and metastatic spread." (PMID 39000413, 2024). "In addition, a significant induction of ferroptosis-related genes (Ptgs2, Alox15 and Hmox1) was detected in tumor samples after treatment with RSL3 + iron, thus confirming the activation of the ferroptotic process inside the tumor mass." (PMID 36872341, 2023). "In addition, HBx might increase the activity of Cyclooxygenase-2 (COX-2, PTGS2), which leads to tumor cell invasion, and activate both MT1-MMP expression and cell invasion." (PMID 37361218, 2023). "Immunohistochemistry (IHC) analysis of the expression of prostaglandin-endoperoxide synthase-2 (PTGS2), a marker for the assessment of oxidative stress and ferroptosis in vivo, indicated the combination effect of knocking down USP8 and erastin treatment in triggering tumor ferroptosis in vivo." (PMID 37051673, 2023). "Interestingly, although we did not observe an increase in PTGS2 expression in tumor tissue, there was a weak positive correlation between CTLA4 in normal tissues and HGSOC." (PMID 38201508, 2023). "Other studies showed that tumor cells with ferroptosis could release large amounts of PGE2 (prostaglandin E2), which may be related to the upregulation of prostaglandin endoperoxide synthase 2 (PTGS2)." (PMID 36552889, 2022). "Interestingly, the halt in proliferation largely coincided with the point at which Ptgs2 upregulation began, with no drug in the wide-ranging library greatly inducing Ptgs2 without diminishing tumor cell proliferation." (PMID 35440553, 2022). "PTGS2 activation produces prostaglandin E2 (PGE2), which acts on a number of cell signaling pathways involving cell proliferation, angiogenesis, apoptosis, invasion, and immunosuppression which could increase tumor progression." (PMID 34136395, 2021). "PTGS2 up-regulation by DAC was also detected using Drug Perturbation Signatures in the cMAP dataset, indicating the potential of DAC + paracetamol co-treatment could be applicable to other tumour types." (PMID 33359448, 2021). "In last years, prostaglandin-endoperoxide synthase 2 (PTGS2) (also known as COX2), an inducible enzyme involved in the synthesis of prostaglandins that contributes to inflammation, angiogenesis, immune evasion and therapy resistance, has also been widely investigated in the tumor context." (PMID 34067294, 2021).